NDUFC1 (NADH:ubiquinone oxidoreductase subunit C1)
Description:
Accessory subunit of the mitochondrial membrane respiratory chain NADH dehydrogenase (Complex I), that is believed not to be involved in catalysis. Complex I functions in the transfer of electrons from NADH to the respiratory chain. The immediate electron acceptor for the enzyme is believed to be ubiquinone.
Synonyms: KFYI
Tractability: Small molecule: an approved drug acts on it; a structure with a bound ligand is known. Antibody: UniProt predicts a signal peptide or a membrane-spanning region. PROTAC: ubiquitination databases record sites on it.
Gene: Protein-coding gene on chromosome 4 (139,266,880 to 139,302,564, reverse strand). Ensembl gene ENSG00000109390.
Subcellular location: Mitochondrion inner membrane
Subcellular location (Human Protein Atlas): Mitochondria
Pathways (Reactome):
Metabolism: Complex I biogenesis; Respiratory electron transport
Gene Ontology:
Molecular function: NADH dehydrogenase (ubiquinone) activity
Biological process: aerobic respiration; mitochondrial electron transport, NADH to ubiquinone; proton motive force-driven mitochondrial ATP synthesis; proton transmembrane transport
Cellular component: mitochondrial inner membrane; mitochondrion; respiratory chain complex I
Genetic constraint (gnomAD): Loss-of-function variants: 7 observed, 8.3 expected, observed/expected ratio (o/e) 0.84, 90% interval 0.48 to 1.56. That is too few expected variants to judge how well the gene tolerates losing a copy. Missense variants: 89 observed, 66.15 expected, observed/expected ratio (o/e) 1.35, 90% interval 1.13 to 1.61. Synonymous variants: 46 observed, 31.04 expected, observed/expected ratio (o/e) 1.48, 90% interval 1.17 to 1.85.
Homologues: Orthologues: rabbit NDUFC1 (88% identical), guinea pig NDUFC1 (82% identical), rat Ndufc1 (76% identical), mouse Ndufc1 (75% identical), dog NDUFC1 (64% identical), pig NDUFC1 (57% identical), tropical clawed frog NDUFC1 (39% identical).
Diseases named in the same sentence as NDUFC1 in open-access papers:
NDUFC1 is named in the same sentence as 13 diseases in open-access papers, as found by Europe PMC text mining. Sharing a sentence is not in itself a finding about the gene and the disease. The quoted sentences say what the papers report.
hepatocellular carcinoma (5 papers, 2022 to 2026). A malignant tumor that arises from hepatocytes. "NDUFC subunits contribute to the structural stability and biogenesis of complex I; the knockdown of NDUFC1 has been demonstrated to inhibit cell proliferation, migration, and invasion in hepatocellular carcinoma." (PMID 41614941, 2026). "Elevated levels of NDUFC1 also predicted unfavourable prognosis of hepatocellular carcinoma patients." (PMID 39533394, 2024). "The downregulation of NDUFC1 expression significantly inhibits the proliferation of hepatoma cells and increases the number of apoptotic cells in liver cancer." (PMID 37409345, 2023). "The expression and functional roles of NDUFC1 in hepatocellular carcinoma (HCC) remain unknown." (PMID 36119539, 2022).
gastric cancer (3 papers, 2021 to 2024). A primary or metastatic malignant neoplasm involving the stomach. "Herein, NDUFC1 knockdown induced gastric cancer cells G2/M phase arrest through regulation of cyclin B1/Cdk1 complex." (PMID 34966665, 2021). "Mice xenograft model was further utilized to verify the inhibition of gastric cancer by NDUFC1 knockdown in vivo." (PMID 34966665, 2021). "Human gastric cancer cell lines with NDUFC1 knockdown were constructed to reveal the effects of NDUFC1 depletion on cell proliferation, cell apoptosis, cell cycle, and cell migration of gastric cancer cells." (PMID 34966665, 2021). "Relationship between NDUFC1 expression and tumor characteristics in patients with gastric cancer analyzed by Spearman rank correlation analysis." (PMID 34966665, 2021). "The expression levels of NDUFC1 in tumor tissues of 88 patients with gastric cancer were detected, compared with normal tissues, and statistically analyzed with tumor characteristics." (PMID 34966665, 2021). "In conclusion, our studies identified NDUFC1 as a tumor promotor of gastric cancer, which was upregulated in gastric cancer and thus promoting gastric cancer through regulation of cell proliferation, cell apoptosis, cell cycle and cell migration." (PMID 34966665, 2021). "To investigate how NDUFC1 influences the development of gastric cancer, we carried out a range of experiments to investigate cell proliferation, cell apoptosis, and cell cycle in MGC-803 and SGC-7901 cells with or without NDUFC1 knockdown." (PMID 34966665, 2021). "In this study, we found that NDUFC1 was significantly upregulated in gastric cancer tissues compared with normal tissues." (PMID 34966665, 2021). "To investigate the role of NDUFC1 in the development of gastric cancer, we used immunohistochemical (IHC) analysis to compare the expression of NDUFC1 in tumors collected from patients with gastric cancer and those collected from normal tissues." (PMID 34966665, 2021). "Collectively, these results indicated that we had successfully established cell models of gastric cancer in which NDUFC1 had been knocked down." (PMID 34966665, 2021). "Otherwise, the downregulation of PIK3CA, a well-known oncogene, was also observed in MGC-803 cells with NDUFC1 knockdown and supposed to participate in the NDUFC1 induced regulation of gastric cancer." (PMID 34966665, 2021). "Expression patterns of NDUFC1 in gastric cancer tissues and normal tissues revealed in immunohistochemistry analysis." (PMID 34966665, 2021). "In this study, we presented the first report of the relationship between NDUFC1 expression and development of gastric cancer." (PMID 34966665, 2021). "Our suspicion was that NDUFC1 knockdown blocked gastric cancer’s progression via PI3K/AKT signaling pathway." (PMID 34966665, 2021). "Next, we used the Chi-squared test to evaluate the relationship between NDUFC1 expression levels and specific tumor characteristics in gastric cancer patients." (PMID 34966665, 2021). "The results indicated that overexpressed NDUFC1 in gastric cancer was related to more serious tumor infiltrates, a higher risk of lymphatic metastasis, a higher proportion of positive lymph nodes, and a more advanced tumor stage." (PMID 34966665, 2021). "From these, we speculated that NDUFC1 downregulation might suppress gastric cancer’s progression via PI3K/AKT signaling pathway." (PMID 34966665, 2021). "Collectively, these results showed that NDUFC1 played a role in the development of gastric cancer." (PMID 34966665, 2021). "NDUFC1 mRNA level in gastric cancer cell lines was determined by qRT-PCR." (PMID 34966665, 2021). "Next, we attempted to verify the roles of NDUFC1 in gastric cancer in vivo." (PMID 34966665, 2021). "IHC analysis (P <0.05) showed that NDUFC1 was significantly upregulated in gastric cancer tissues." (PMID 34966665, 2021). "Despite of these results, the role of NDUFC1 in cancer, including gastric cancer was rarely seen and remains unknown." (PMID 34966665, 2021).
gastric cancer (continued). "Taken together, our study indicated that targeting NDUFC1 could open innovative perspectives for new multi-targeting approaches in the treatment of gastric cancer." (PMID 34966665, 2021). "Using Human apoptosis antibody array, we found that NDUFC1 knockdown may promote gastric cancer cell apoptosis through downregulating Bcl-2, clAP-2, Survivin, sTNF-R1, and XIAP." (PMID 34966665, 2021). "Relationship between NDUFC1 expression and tumor characteristics in patients with gastric cancer." (PMID 34966665, 2021). "All the results provided clear evidence that NDUFC1 knockdown could obviously alleviate the development of gastric cancer and may be a therapeutic target for the treatment of gastric cancer." (PMID 34966665, 2021). "Collectively, these results indicated that NDUFC1 may play a critical role in the development and progression of gastric cancer." (PMID 34966665, 2021). "Further detection of the expression levels of CDK6 and Cyclin D1, which plays critical roles in cell cycle and is well known to be involved in the development of various types of human cancers including gastric cancer, showed downregulated expression induced by NDUFC1 knockdown." (PMID 34966665, 2021). "After confirming that NDUFC1 played a role in the development and metastasis of gastric cancer, we next turned our attention to mechanisms that might be responsible for these effects." (PMID 34966665, 2021). "Targeting NDUFC1 could be a potential approach in the treatment of gastric cancer." (PMID 37062830, 2023). "We speculated that NDUFC1 might regulate gastric cancer via PI3K-Akt signaling pathway as well." (PMID 34966665, 2021). "Therefore, we identified NDUFC1 as a tumor promotor in gastric cancer, which may be a promising therapeutic target for treatment of gastric cancer." (PMID 34966665, 2021). "Our previous results suggested that NDUFC1 may act to promote gastric cancer." (PMID 34966665, 2021). "Therefore, NDUFC1 may be considered as a novel therapeutic target and its knockdown may serve as a promising strategy of gastric cancer treatment." (PMID 34966665, 2021). "We also used qPCR to detect the background expression of NDUFC1 in human normal gastric mucosal cell GES1 and both human gastric cancer cell lines MGC-803 and SGC-7901, showing that the mRNA levels of NDUFC1 in gastric cancer cell lines were higher than that of NDUFC1 in GES1 cells." (PMID 34966665, 2021).
liver cancer (2 papers, 2022 to 2023). An epithelial or non-epithelial malignant neoplasm that arises from the liver. "The expression of NDUFC1 messenger RNA (mRNA) in human liver cancer cell lines BEL-7404 and SK-HEP-1 was assessed by qRT-PCR, and the results indicated that NDUFC1 mRNA was highly expressed in both cell lines." (PMID 36119539, 2022).
sarcopenia (2 papers, 2023 to 2025). Progressive decline in muscle mass due to aging which results in decreased functional capacity of muscles. "Our findings indicate the cuproptosis-related genes, PDHA1, DLAT, PDHB, and NDUFC1 are the diagnostic biomarker for sarcopenia, which provide evidence concerning the role of cuproptosis in sarcopenia." (PMID 37007946, 2023). "The four hub genes (PDHA1, DLAT, PDHB, and NDUFC1) were included to construct a diagnostic model for sarcopenia." (PMID 37007946, 2023). "According to the results of ROC analysis, PDHA1, DLAT, PDHB, and NDUFC1 were selected as the potential promising diagnostic biomarkers of sarcopenia." (PMID 37007946, 2023). "Intersection of DEGs, WGCNA and CRGs yielded four core genes (PDHA1, DLAT, PDHB, and NDUFC1) as potential biomarkers for the prediction of sarcopenia." (PMID 37007946, 2023). "In this study, the molecular docking results suggested that metformin could be a potential therapeutic drug for sarcopenia by targeting NDUFC1." (PMID 37007946, 2023). "NDUFC1, a key gene related to cuproptosis, is also downregulated among the sarcopenia subjects." (PMID 37007946, 2023). "Finally, metformin was identified as a promising strategy of sarcopenia treatment via targeting NDUFC1." (PMID 37007946, 2023). "In this study, the drug analysis showed that metformin is a potential therapeutic agent on sarcopenia via binding to NDUFC1, which may have significant implications for possible therapeutic interventions on sarcopenia, however, the precise mechanism by which metformin act remains further research." (PMID 37007946, 2023). "A total of four overlapping genes were extracted as the hub genes involved in sarcopenia and cuproptosis, which were PDHA1, DLAT, PDHB and NDUFC1." (PMID 37007946, 2023). "A total of four possible hub genes of sarcopenia were screened, namely, PDHA1, DLAT, PDHB, and NDUFC1." (PMID 37007946, 2023). "The present study inferred the significance of mitochondrial dysfunction in the progression of sarcopenia, and the four cuproptosis-related genes, PDHA1, DLAT, PDHB, and NDUFC1, may serve as the potential targets for further therapeutic intervention." (PMID 37007946, 2023).
breast carcinoma (1 paper, 2024). "NDUFC1, important in mitochondrial metabolism, has been found to be more critical in ER + breast cancer cells, suggesting a metabolic vulnerability in this subtype." (PMID 39720180, 2024).
endothelial dysfunction (1 paper, 2025). In vascular diseases, endothelial dysfunction is a systemic pathological state of the endothelium (the inner lining of blood vessels) and can be broadly defined as an imbalance between vasodilating and vasoconstricting substances produced by (or acting on) the endothelium. "Dysfunction in NDUFC1 may reduce the efficiency of the electron transport chain, leading to decreased ATP production, which can exacerbate endothelial dysfunction and smooth muscle cell impairment in blood vessels, contributing to the progression of high BP." (PMID 41480028, 2025).
Huntington disease (1 paper, 2012). Huntington disease (HD) is a rare neurodegenerative disorder of the central nervous system characterized by unwanted choreatic movements, behavioral and psychiatric disturbances and dementia. "For example: Huntington’s disease (NDUFA7, NDUFC1, NDUFB2, NDUFB3, NDUFA8), atrophy of optic nerve (NDUFS4) and Leigh syndrome (NDUFS7, NDUFA2, NDUFS4)." (PMID 23028713, 2012).
lentivirus infection (1 paper, 2022). Virus diseases caused by the Lentivirus genus. "Annexin V double staining and flow cytometric analysis were used on BEL-7404 and SK-HEP-1 cells following lentivirus infection to further to confirm the effect of NDUFC1 silencing on cell apoptosis." (PMID 36119539, 2022).
tumor (7 papers, 2020 to 2024). "NDUFC1 overexpression was found to be related to more serious tumor infiltration, higher risk of lymphatic metastasis, whereas NDUFC1 downregulation promoted the inhibitory effects on cell proliferation and migration via the PI3K/Akt pathway." (PMID 37062830, 2023). "Moreover, further statistical analysis revealed that high NDUFC1 expression was associated with more serious tumor infiltration, more advanced tumor stage and higher risk of lymphatic metastasis." (PMID 34966665, 2021). "This demonstrated that high expression levels of NDUFC1 were positively correlated with more serious tumor infiltrates, a higher risk of lymphatic metastasis, a higher proportion of positive lymph nodes, and a more advanced tumor stage, which was confirmed by Spearman rank correlation analysis." (PMID 34966665, 2021). "Next, we used wound-healing and transwell assays to investigate the effects of NDUFC1 knockdown on cell migration ability and tumor metastasis." (PMID 34966665, 2021). "We found that the knockdown of NDUFC1 significantly slowed down the rate of tumor growth in vivo (P <0.01)." (PMID 34966665, 2021). "Notwithstanding, we still believe NDUFC1 could be a target for tumor progression by inhibiting senescence and affecting Complex I–induced mitochondrial metabolism in HCC." (PMID 36119539, 2022). "We also injected D-Luciferin into mice so that we could monitor the suppression of tumor growth in response to NDUFC1 knockdown by fluorescence imaging (P <0.05)." (PMID 34966665, 2021). "Collectively, these results suggested that the knockdown of NDUFC1 could restrain tumor growth in vivo." (PMID 34966665, 2021). "NDUFC1 may serve as a target for further intervention and anti-tumor effect." (PMID 36119539, 2022). "We analyzed the expression of genes in tumor and normal samples, and the results showed that NDUFS1, NDUFS2, NDUFC1, and EPAS1 were downregulated in CRC, and SLC7A11, OXSM, LRPPRC, NDIFA11, NUBPL, and CONT1 were upregulated in CRC." (PMID 37978247, 2023). "The top genes in cold tumor are ARF1, PDIA3, ALDOA, FKBP2, NDUFS5, NDUFC1, COX7A2, C14orf2, LNX1, and BTBD6." (PMID 33816503, 2021). "In addition, we found that many genes associated with ATP synthesis, such as ATP5F1D, ATP5ME, and ATP5MF, and genes associated with NADH oxidation, such as NDUFS8, NDUFB10, and NDUFC1, were overexpressed in LIHC and LUAD tumor tissues." (PMID 33262783, 2020).
cancer (4 papers, 2021 to 2024). A tumor composed of atypical neoplastic, often pleomorphic cells that invade other tissues. "First, we have discovered that NDUFC1 is involved in regulating cancer-associated pathways and characteristics but lacks intervention in pathways." (PMID 36119539, 2022). "However, the function of NDUFC1 and its relationship with human diseases, especially cancer, are rarely reported and still largely unknown." (PMID 34966665, 2021). "In our study, we found that silence NDUFC1 may inhibit the function of Complex I and induce ROS in HCC and could mediate the serious antitumor progression and senescence through various cancer related pathways." (PMID 36119539, 2022).
neurodegenerative disease (1 paper, 2025). A disorder of the central nervous system characterized by gradual and progressive loss of neural tissue and neurologic function. "The mitochondrial dysfunction in the neurodegenerative diseases cluster (Cluster 4) comprises 95 genes, including several key mitochondrial protein genes acting as pivotal hub genes, such as Sdhb, Ndufa4, Ndufb4c, Ndufb4b, Ndufv3, Ndufa9, Ndufc1, Ndufs5, Ndufb4, Ndufa12, Ndufa11, and Ndufb1." (PMID 41294802, 2025).
NDUFC1 also shares sentences with these, for which no sentence is quoted: Alzheimer disease (1 paper); Leigh syndrome (1).